GDNF (glial cell derived neurotrophic factor)
Diseases named in the same sentence as GDNF in open-access papers (continued):
Sharing a sentence is not in itself a finding about the gene and the disease.
Hirschsprung disease (18 papers, 2009 to 2025). Hirschsprung disease (HSCR) is a congenital intestinal motility disorder that is characterized by signs of intestinal obstruction due to the presence of an aganglionic segment of variable extent in the terminal part of the colon. "RET is a transmembrane protein, which binds the members of the glial cell‐derived neurotrophic factor (GDNF) family, and is most commonly implicated in Hirschsprung's disease." (PMID 32808420, 2020). "Ret has multiple, well-described roles in development of the enteric nervous system, as a receptor for GDNF, and mutations in this gene are an important cause of Hirschsprung disease." (PMID 28558017, 2017). "Otherwise, the very few studies that have investigated this question in a more detailed manner were mostly restricted to Peyer’s patches, based on the prior discovery that the Hirschsprung disease-associated signaling pathway GDNF-RET is key for the development of this lymphoid site in the ileum." (PMID 38744932, 2024). "The idea answer is: Coding sequence mutations in RET, GDNF, EDNRB, EDN3, and SOX10 are involved in the development of Hirschsprung disease." (PMID 40766492, 2025). "Our findings implicate a dual lineage origin for the ENS with mechanistically distinct features, and illuminate the consequences of Edn3 and GDNF signaling that account for Hirschsprung disease when either is compromised." (PMID 39641974, 2024). "This study also documents decreases in protein levels of both BMP-2 and GDNF in gut samples of patients with Hirschsprung’s disease." (PMID 35459867, 2022). "No alteration in the gene dosage was observed in the other three genes related to Hirschsprung disease (GDNF, EDN3 and ZFHX1B) in all controls, thyroid samples and thyroid cell lines." (PMID 31288802, 2019). "Collectively, the results imply that mutation in GDNF, NRTN or RET reduce the affinity for GFRA1 interaction, resulting in Hirschsprung’s disease." (PMID 29617307, 2018). "GDNF is established to be important in the development of the enteric nervous system and Hirschsprung disease." (PMID 22132166, 2011). "In addition, Schwann cell precursors associated with extrinsic nerves have been identified as a source of new neurons after GDNF treatment in Hirschsprung Disease mouse models and in zebrafish." (PMID 35563190, 2022). "GDNF treatment after birth provides a possible treatment approach for Hirschsprung Disease patients and might reduce the need for the surgical removal of the aganglionic gut region or result in better functional outcomes after surgery." (PMID 35563190, 2022). "The application of GDNF to the aganglionic rectum was able to stimulate these glia to proliferate and generate enteric neurons, thereby restoring gut motility and ensuring survival of a number of different transgenic mouse models of Hirschsprung disease." (PMID 35111752, 2021). "Although a GFRA1 mutation has not been found in Hirschsprung’s patients, Hirschsprung’s disease has been observed in heterozygous GDNF+/− mice." (PMID 29617307, 2018). "In children with Hirschsprung’s disease, mutations of both the RET proto-oncogene have been described, encoding a receptor tyrosine kinase that is thought to be involved in neural crest migration and proliferation, and RET ligand, glial cell line-derived neurotrophic factor (GDNF)." (PMID 19794884, 2009). "In this tissue, GDNF promotes the formation of an extensive autonomously functioning nervous plexus; in the absence of GDNF signaling pathways, this plexus fails to develop, leading to Hirschsprung disease." (PMID 28878618, 2017). "However, why these enteric glial cells in the aganglionic colon fail to differentiate into neurons in the absence of exogenous GDNF, and whether they can be channelled as a form of cell therapy for the treatment of Hirschsprung disease in larger mammals remains to be investigated further." (PMID 35111752, 2021).
retinal degeneration (17 papers, 2009 to 2025). Degeneration of the retina. "When the luciferase cDNA was substituted with a transgene encoding GDNF, the level of transgene expression achieved was sufficient to enable histological rescue of blue light induced retinal degeneration at 77 days post injection." (PMID 24278479, 2013). "Subretinal injection, slow-release devices, adenoviral delivery, or cell-based delivery of GDNF have been shown to delay photoreceptor loss in several different models of retinal degeneration." (PMID 19461934, 2009). "The role of GDNF in the protection and regeneration of retinal cells has been observed in several studies such as optical nerve crush, rhodopsin knockout mice or retinal degeneration mouse model." (PMID 40594667, 2025). "Using the well-established Royal College of Surgeons (RCS) rat model of retinal degeneration, we have shown that fNPCs can protect vision and photoreceptors and that GDNF-secreting fNPCs provide enhanced protection." (PMID 37084724, 2023). "This study examined vision protection by human neural progenitor cells (hNPC) and hNPC engineered to express GDNF (hNPCGDNF) in a rat model of retinal degeneration at a disease stage relevant to clinical translation." (PMID 37786347, 2023). "In the eye, GDNF is mainly expressed in the retina and has potential therapeutic value by providing neuroprotection in the context of retinal degeneration." (PMID 34803580, 2021). "These authors then extended to testing the ability of the ShH10 vector to deliver GDNF to the retina via Müller cells, and its ability to modulate retinal degeneration in the S334-4ter rat model of retinitis pigmentosa." (PMID 33505247, 2020). "Mutant mice lacking GDNF-family ligands or the receptor for these ligands, Ret, manifest retinal degeneration in early adulthood, a process resembling defective GDNF signaling and retinal degeneration in FASKO retina." (PMID 29321376, 2018). "GDNF has also been applied in preclinical and clinical trials to treat CNS degeneration and has attracted attention in ameliorating retina degenerations." (PMID 27441692, 2016). "Considering the heterogeneity of etiological factors involved in retinal degeneration, in addition to the cost of developing gene-specific therapy, the benefit of delivering neuroprotective factors, such as GDNF, cannot be ignored." (PMID 24278479, 2013). "Of particular interest in the setting of retinal degeneration is the use of tissue-specific progenitors, namely RPCs, to deliver neurotrophic factors with known neuroprotective activity, a notable example being GDNF." (PMID 21203407, 2010). "ES cells engineered to secrete GDNF exerted a neuroprotective effect for at least three months on retinal structure in the TgN S334ter rat model of retinal degeneration." (PMID 19461934, 2009). "No studies to date have reported on local or systemic GDNF measurements in retinal degeneration models treated with GDNF." (PMID 19461934, 2009). "In addition, it seems that GDNF acts on retinal degeneration both indirectly, stimulating the photoreceptor survival, and directly, after intravitreal injection of microspheres containing GDNF." (PMID 34360760, 2021). "The results demonstrated that mES cells, which were engineered to secrete GDNF and were delivered by intravitreal injection to the TgN S334ter rat model of retinal degeneration, have a significant effect on prolonging photoreceptor survival compared to the parent cell line or sham injection." (PMID 19461934, 2009). "When this vector was used to deliver a GDNF transgene in the diseased retina, they were able to demonstrate long-term expression of therapeutic and safe levels of GDNF for up to 5 months, and this was accompanied by a slowdown in retinal degeneration, as assessed by electroretinogram and histology." (PMID 33505247, 2020). "Remarkably, GDNF increases AMD RPE phagocytosis, indicating hNPCGDNF has the potential to treat retinal degeneration including both RP and AMD." (PMID 37786347, 2023).
retinal degeneration (continued). "Human neural progenitor cells (hNPC) and hNPC engineered to stably express GDNF (hNPCGDNF) were subretinally injected into the Royal College of Surgeon (RCS) rats, a well-established model for retinal degeneration, at early and later stages of the disease." (PMID 37786347, 2023). "Many of the factors involved in this “dialogue” have been identified; MGC release several molecules, such as FGF, GDNF, DHA, and LIF, that rescue PHRs in different models of retinal degeneration." (PMID 31402853, 2019). "Moreover, a combination of GDNF and CNTF was reported to afford higher protection to photoreceptors in a retinal degeneration (rd) mouse." (PMID 34803580, 2021). "As the retinal degeneration starts, the activated microglia invade the degenerated photoreceptor layer and reduce the expressions of neurotrophic factors including nerve growth factor (NGF), ciliary neurotrophic factor (CNTF), and glial cell line-derived neurotrophic factor (GDNF)." (PMID 37728589, 2024). "However, the higher GDNF levels after six gel injections when compared to three gel injections did not yield more protection; this may be due to the retinal degeneration model used." (PMID 39330275, 2024).
diabetes (16 papers, 2013 to 2026). "Diabetes mellitus was another factor significantly linked to decreased GDNF protein expression in our cohort." (PMID 40722606, 2025). "GDNF treatment ameliorates diabetes associated with Müller cells impairment, but also promotes the synthesis of endogenous GDNF and its receptors." (PMID 32252363, 2020). "Up-regulated GDNF in the diabetic tissues could reflect diabetes-enhanced protein glycosylation, a process required for correct processing of the GDNF protein, but also closely linked to oxidative stress." (PMID 37754589, 2023). "Testing our evolutionary‐based hypothesis will provide the foundation for future development of GDNF‐based treatment options for impaired wound healing and tissue regeneration caused by diabetes, burns and scarring, which largely reflect functional fibroblasts." (PMID 35020233, 2022). "In the analysis stratified by diabetes type, two biomarkers were positively associated with cognitive-affective symptoms in T2D (CCL25, GDNF)." (PMID 39799156, 2025). "In the current study, the induction of diabetes significantly reduced the gene expression of the neuroprotective GDNF in the brain tissue of the rats in the positive control group." (PMID 40257540, 2025). "We measured the GDNF levels in patients with degenerative stenosis and assessed the impact of BMI, smoking status, and the presence of diabetes." (PMID 40722606, 2025). "This study demonstrates a significant reduction in GDNF protein levels in the ligamentum flavum of patients with lumbosacral spinal stenosis, which appears to be influenced by key modifiable factors such as obesity, diabetes mellitus, and smoking." (PMID 40722606, 2025). "We investigated whether the expression profiles of GDNF at both the mRNA and protein levels were influenced by gender, BMI, diabetes status, smoking, and alcohol consumption." (PMID 40722606, 2025). "GDNF is a substance secreted by enteric glial cells, which can nourish enteric neurons under normal physiological conditions and protect them under pathological conditions such as diabetes." (PMID 38699694, 2024). "Additionally, several researches have indicated that the EGC were lost and the expression of glial cell line-derived neurotrophic factor (GDNF) was significantly decreased in diabetes rats." (PMID 24860604, 2014). "Interestingly, rats showed low T levels, suggesting that hypotestosteronemia and diabetes mellitus might interfere with GC proliferation through disruption of the GDNF signaling pathway." (PMID 38961093, 2024). "For another eight biomarkers (TNFβ, GDNF, IL-18R1, LIF-R, CD244, CD6, FGF-5, IFNγ), a significant interaction by diabetes type was observed." (PMID 39799156, 2025). "Additionally, patients who smoked or had diabetes showed significantly lower GDNF levels compared to non-smokers and those without diabetes (p = 0.03 and p = 0.02, respectively)." (PMID 40722606, 2025). "Bioinformatic analysis showed that all investigated proteins (GDNF, iNOS, SOD isoforms) share subcellular localization in the mitochondrial permeability transition pore complex, along with major melatonin receptor MNTR1A protein, pointing to their importance for the observed effects in diabetes." (PMID 37754589, 2023). "In rodent models of diabetes and high‐fat diet, inulin supplementation did not significantly alter glial markers (GFAP, GDNF) in the colon or brain, nor did it affect myenteric neuronal subpopulations or enteric glial cells, despite reducing inflammation and improving colonic motility." (PMID 41486750, 2026).
Huntington disease (16 papers, 2009 to 2025). Huntington disease (HD) is a rare neurodegenerative disorder of the central nervous system characterized by unwanted choreatic movements, behavioral and psychiatric disturbances and dementia. "More recently, liposomal glial-derived neurotrophic factor (GDNF) and FUS-induced BBB opening were used for treatment in a mouse model of Huntington’s disease." (PMID 31798453, 2019). "Neurotrophic factors such as glial cell line-derived neurotrophic factor (GDNF), brain-derived neurotrophic factor (BDNF), and neurturin, for example, all appear to protect against the striatonigral degeneration in Huntington’s disease." (PMID 30524706, 2018). "In one instance, neural stem cells (NSC) genetically engineered to overexpress glial-cell derived neurotrophic factor (GDNF) and also to express the luciferase gene have been tracked, quantified, and characterized in vivo upon grafting to the mouse brain in a Huntington's disease model (HD)." (PMID 25147799, 2014). "In vitro and in vivo data suggest that treatment with neurotrophic factors such as NGF, glial cell line-derived neurotrophic factor (GDNF), brain-derived neurotrophic factor (BDNF) and several neurotrophins (NTs) could induce survival of specific neuronal populations in Huntington's disease." (PMID 21349151, 2011). "Considering this, GDNF and CDNF could be of particular interest for PD, NGF could be of particular interest for AD, and BDNF, because of its rich expression in the brain, could provide support for AD, PD, spinal cord injury, multiple sclerosis (MS), and Huntington’s disease (HD)." (PMID 37047292, 2023).
Hyperglycemia (16 papers, 2013 to 2025). An increased concentration of glucose in the blood. "Hyperglycemia and associated mitochondrial dysfunction may downregulate GDNF expression through enhanced oxidative stress." (PMID 40722606, 2025). "Hyperglycemia state can reduce the release of GDNF, thereby mitigating the protective effect of transmitters and causing neurotoxicity." (PMID 40380290, 2025). "Consistent with this, it has been revealed that T1D-induced hyperglycemia directly affects Sertoli cell production of growth factors, such as glial cell line-derived neurotrophic factor (GDNF)." (PMID 38164482, 2024). "In the current study, we also found that GDNF was significantly down-regulated in hyperglycemia-treated EGC; while circVPS13A overexpression or miR-182 inhibition significantly enhanced GDNF expression." (PMID 35880571, 2022). "Consistently,GDNF silencing attenuated the protective effect of circVPS13A overexpression or miR-182 inhibition on hyperglycemia-induced EGC cytotoxicity and apoptosis in CRL-2690 cells." (PMID 35880571, 2022). "GDNF has ameliorating effects on hyperglycemia-induced diabetic kidney damage by increasing apoptotic resistance." (PMID 36056427, 2022). "Further study also revealed that miR-182 inhibitor or circVPS13A overexpression significantly enhanced GDNF expression at the protein level in hyperglycemia-treated EGC." (PMID 35880571, 2022). "Maternal hyperglycemia can inhibit morphogenesis of ureteric bud branching, Glial cell line-derived neurotrophilic factor (GDNF) is a key regulator of the initiation of ureteric branching." (PMID 23468876, 2013). "Among them, EGR-1 has been demonstrated as a regulatory protein for GDNF and essential for tubulogenesis in hyperglycemia-induced renal embryopathy." (PMID 23468876, 2013). "A previous study demonstrated that glucose concentration-dependent expression of GDNF and RET in human PC cells correlates with alterations of cell proliferation, suggesting GDNF and RET as hyperglycemia underlying mechanism inducing PC progression." (PMID 24303367, 2013). "Our in vivo microarray, real time-PCR and confocal morphological observation confirmed apoptosis in hyperglycemia-induced fetal nephropathy via activation of the GDNF/MAPK/EGR-1 pathway at E12-E15." (PMID 23468876, 2013). "We further analyzed EGR-1 contribution to hyperglycemia down-regulating GDNF-induced migration to HRPTE cells and GDNF-dependent phosphorylation of cRaf, MEK and ERK by small interfering RNA (siRNA) of EGR-1-mediated experiments." (PMID 23468876, 2013). "In addition, it was reported previously that GDNF rescues hyperglycemia-induced diabetic enteric neuropathy through activation of the PI3K/Akt pathway." (PMID 40257540, 2025). "Meanwhile,GDNF silencing attenuated the protective effect of miR-182 inhibitor or circVPS13A overexpression on hyperglycemia-induced EGC cytotoxicity and apoptosis in CRL-2690 cells, indicating that circVPS13A overexpression acts similarly to that of miR-182 inhibitor." (PMID 35880571, 2022). "In addition, GDNF expression was down-regulated in hyperglycemia-treated EGC, and negatively correlated with miR-182 but positively correlated with circVPS13A." (PMID 35880571, 2022). "Glucose concentrations could alter the expression of GDNF and RET in a concentration-dependent manner, and hyperglycemia could upregulate the interaction between GDNF and the RET ligand receptor." (PMID 24864247, 2014). "Furthermore, knockdown of ERG-1 by siRNA abolished hyperglycemia suppressed GDNF-induced migration of HRPTE cells." (PMID 23468876, 2013). "Hyperglycemia enhanced, GDNF-induced DNA damage was determined by comet assay." (PMID 23468876, 2013). "Subsequently, we examined whether hyperglycemia suppressed GDNF-induced epithelial cell migration." (PMID 23468876, 2013). "To determine whether EGR-1 mRNA expression was up-regulated by hyperglycemia, we exposed HRPTE cells to GDNF in high glucose concentration." (PMID 23468876, 2013).
Hyperglycemia (continued). "This may also explain how hyperglycemia-induced EGC apoptosis alters the gastrointestinal motility because increase of apoptosis of EGC may damage the function of EGC and reduce the production of GDNF." (PMID 30140011, 2018).